RNU6-1318P (RNA, U6 small nuclear 1318, pseudogene)
Gene: Small nuclear RNA gene on chromosome 1 (100,000,637 to 100,000,739, reverse strand). Ensembl gene ENSG00000202259.
Homologues: Orthologues: chimpanzee U6 (98% identical), macaque U6 (94% identical), dog U6 (89% identical), rabbit U6 (81% identical). Paralogues in human: RNU6-664P (90% identical), RNU6-38P (89% identical), RNU6-698P (89% identical), RNU6-774P (89% identical), RNU6-86P (89% identical), RNU6-1125P (88% identical), RNU6-1309P (88% identical), RNU6-28P (88% identical), RNU6-560P (88% identical), RNU6-1026P (87% identical), RNU6-1227P (87% identical), RNU6-1316P (87% identical), and 1284 more.